DEK (DEK proto-oncogene)
Diseases named in the same sentence as DEK in open-access papers (continued):
Sharing a sentence is not in itself a finding about the gene and the disease.
tumor (continued). "In addition to promoting tumor growth and invasion, DEK has potential pro-inflammatory properties." (PMID 28423581, 2017). "The reports that involve DEK as a nuclear protein related to cell metabolism by changing supercoiled DNA and maintaining heterochromatin structure along DNA transcription could explain tumor aggressive behaviour and chemoresistance properties." (PMID 25515240, 2014). "Moreover, as DEK may be present at higher levels in immature cells than in differentiated counterparts, it could also aid in gauging the differentiation potential of tumor cells." (PMID 23902796, 2013). "Therefore, DEK over-expressing epithelial cells may produce and secrete several small molecules, such as S1P and lactate, in addition to the protein cytokines investigated here, to promote the M2 polarization of TAMs to drive tumor progression." (PMID 32708944, 2020). "Together, these results expand the impact of our results to other pathologies, but also emphasize tumor-type selectivity in the regulation of CELF1 and DEK." (PMID 29269732, 2017). "Histological analysis further showed that reduced DEK expression in SMMC7221 resulted in fewer and smaller tumor foci in liver section compared to the knockdown control." (PMID 27057626, 2016). "However, whether DEK enhances tumor angiogenesis remains unclear." (PMID 26988756, 2016). "DEK protein levels were analyzed in a panel of 9 human-derived CRC cell lines and compared with the expression in 2 non-tumor mucosa tissues." (PMID 25515240, 2014). "First, we found that HSPA8 and DEK had the strongest correlation with the ESTIMATE score among 36 known histone chaperones, indicating that these histone chaperones are most closely related to tumor immunity in HCC." (PMID 36768989, 2023). "ST1926 treatment down-regulated a group of oncogenic proteins (SLC2A1, SLC25A6, CBX3, DEK, DDX39B) and up-regulated a group of presumably tumor-suppressing proteins (PEBP1, HspBP1); PADI2 and CMPK1, of unknown function in GBM, were also up-regulated." (PMID 37762371, 2023). "In addition, the SPOP protein plays a role as a tumor suppressor that negatively regulates the stability of multiple other oncogenic substrates in PrCa, including AR, SRC-3, c-MYC, ERG, DEK, BRD4 and Trim24." (PMID 34857003, 2021). "Altogether, this study pinpoints DEK as an important mediator of the PARP1/2-dependent response of replicating cells to fork impairment, a previously unrecognized function of DEK which has implications for tumor therapy and warrants further investigation." (PMID 31408463, 2019). "Here, we show that DEK is a key regulator of VEGF expression and tumor angiogenesis." (PMID 26988756, 2016). "Results show that 33 out of 38 (86%) TCC tumor tissues of both low and high grade were positive for the presence of DEK protein with no detectable levels of DEK protein in the adjacent normal tissues." (PMID 21663673, 2011). "We then explored the correlation between the expression of the two genes and the abundance of tumor-infiltrating lymphocytes (TILs) in TISIDB and found that the expression of HSPA8 was positively correlated with the abundance of TILs in HCC, whereas the expression of DEK showed the opposite trend." (PMID 36768989, 2023). "SPOP has been shown to participate in diverse cellular processes and plays tumor suppressive and oncogenic roles in PrCa by targeting different substrates for ubiqutination-mediated proteolysis, including AR, steroid receptor coactivator 3 (SRC-3), DEK, TRIM24, BRD4 and Nanog." (PMID 34857003, 2021). "In addition, while DEK staining was negative in normal bronchial epithelial cells, DEK was overexpressed in tumor cells, mainly in the nuclear compartments." (PMID 32656741, 2020). "One caveat regarding cancer-related interpretation of these results is that many of the experiments are based upon DEK loss of function, and thus only address the requirement for DEK in tumor cell growth and not the contribution of DEK overexpression to tumor growth." (PMID 29538372, 2018).
tumor (continued). "In triple‐negative breast cancer, DEK promoted EMT, tumour metastasis and angiogenesis through the PI3K (phosphatidylinositol 3‐kinases)/ AKT/ mTOR signalling pathway." (PMID 33124760, 2020). "Western blot with VEGF antibody and IHC with an antibody against CD31, a vascular marker, showed that overexpression of DEK promoted VEGF expression and tumor angiogenesis, and HIF-1α knockdown inhibited but not abolished DEK-mediated enhancement of VEGF expression and angiogenesis." (PMID 26988756, 2016). "To explore the role of DEK in human HCC, we assessed the DEK gene expression in HCC clinical samples using microarray data from Gene Expression Omnibus (GEO), which showed that the expression levels of DEK in tumor tissues were elevated compared with the adjacent non-tumor tissues." (PMID 27057626, 2016).
infection (4 papers, 2009 to 2021). The state of being infected such as from the introduction of a foreign agent such as serum, vaccine, antigenic substance or organism. "The same study also observed that DEK, a H3.3 chaperone that regulates H3.3 distribution to HIRA and ATRX/DAXX, associated with the viral genome for most of the first 6 h of infection." (PMID 33909709, 2021). "Either DEK or IRAK1 knockdown alone could induce apoptosis as expected (8–10 fold over control), but the combined effect of IRAK1 shRNA with AdDEKsh infection was greater than that of the respective control cells (20-fold)." (PMID 26527316, 2015).
adenocarcinoma (2 papers, 2012 to 2015). A common cancer characterized by the presence of malignant glandular cells. "Based on the strength of the association between DEK expression and ER status in primary adenocarcinomas (p = 0.04), we decided to focus on the mechanism of 17β-estradiol mediated DEK up-regulation." (PMID 23071688, 2012). "Consistent with their mRNA expression, all NEPC models showed strong nuclear staining of DEK; elevated nuclear DEK staining was also observed in LTL331 compared to other adenocarcinoma models." (PMID 25544761, 2015). "RNA-seq data of this cohort showed that DEK mRNA expression was significantly higher in NEPC tissues when compared to adenocarcinoma (p < 0.001)." (PMID 25544761, 2015). "Since increased DEK expression was observed immediately after host castration, it is possible that DEK is negatively regulated by AR signaling in adenocarcinoma." (PMID 25544761, 2015). "Increased DEK expression in a small proportion of hormonal naïve PCa cases and adenocarcinoma xenograft models suggests that increased DEK expression may be a pre-disposing factor in hormonal naïve cancers during NEPC progression and associated with aggressiveness." (PMID 25544761, 2015). "By comparing gene expression profiles of a transplantable adenocarcinoma line (LTL331) and its NEPC subline (LTL331R), we identified DEK as a potential biomarker and therapeutic target for NEPC." (PMID 25544761, 2015). "We observed significantly increased DEK RNA expression in multiple NEPC models (LTL331R, LTL352 and LTL370) compared to adenocarcinoma models." (PMID 25544761, 2015). "All the benign prostate cases and 158 out of 163 (96.93%) hormonal naïve primary adenocarcinoma cases showed negative expression of DEK protein." (PMID 25544761, 2015). "Interestingly, the increase of DEK expression was only observed in LTL331 but not in other adenocarcinoma models that do not give rise to NEPC after host castration." (PMID 25544761, 2015). "However, this hypothesis was not supported by the lack of DEK post-castration up-regulation in other adenocarcinoma xenograft models (such as LTL313B and LTL418)." (PMID 25544761, 2015).
inflammation (1 paper, 2023). Aberrant reaction of the microcirculation characterized by movement of fluid and leukocytes from the blood into extravascular tissues. "The DEK/ATAD3A/DRP1 signaling axis may mediate the effects of DEK on mitophagy and NLRP3 inflammasome in asthmatic airway inflammation." (PMID 38274803, 2023).
neurodegenerative disease (1 paper, 2022). A disorder of the central nervous system characterized by gradual and progressive loss of neural tissue and neurologic function. "Other recent studies have also identified DEK as a potential target in neurodegenerative diseases." (PMID 36275000, 2022). "Multiple research groups have now suggested that decreased or dysregulated DEK expression could be a driver of neurodegenerative diseases like Alzheimer’s and Huntington’s." (PMID 36275000, 2022).
respiratory diseases (1 paper, 2025). "Overexpression of DEK leads to mitochondrial dysfunction and structural damage, whereas inhibition of DEK can reduce airway inflammation and alleviate respiratory diseases." (PMID 39668431, 2025). "Considering the unclear mechanism of DEK's involvement in airway inflammation, we further studied the relationship between DEK and AR, one of the respiratory diseases." (PMID 39668431, 2025).
DEK also shares sentences with these, for which no sentence is quoted: ovarian carcinoma (4 papers); head and neck squamous cell carcinoma (3); triple-negative breast carcinoma (3); cholangiocarcinoma (2); chronic lymphocytic leukemia (2); colon cancer (2); myelodysplastic syndrome (2); osteosarcoma (2); acute erythroid leukemia (1); acute lymphoblastic leukemia (1); acute megakaryoblastic leukemia (1); Acute myelomonocytic leukemia (1); and basaloid carcinomas (1); astrocytic tumor (1); atherosclerosis (1); brain cancer (1); brain disorder (1); chronic myeloid leukemia (1); cognitive deficits (1); colon adenoma (1); diffuse large B-cell lymphoma (1); dysplasia (1); lung adenocarcinoma (1); Myelodysplasia (1); myeloid neoplasm (1); nasopharyngeal carcinoma (1); oral squamous cell carcinoma (1); plasma cell neoplasm (1); prostatic small cell neuroendocrine carcinoma (1); sarcoidosis (1).
A further 4 diseases each share a sentence with DEK in 1 paper.